MIR3187 (microRNA 3187)
Synonyms: hsa-mir-3187; mir-3187
Gene: MicroRNA gene on chromosome 19 (813,584 to 813,653, forward strand). Ensembl gene ENSG00000263414.
Homologues: Orthologues: chimpanzee MIR3187 (100% identical), macaque MIR3187 (100% identical).